RARB (retinoic acid receptor beta)
Diseases named in the same sentence as RARB in open-access papers (continued):
Sharing a sentence is not in itself a finding about the gene and the disease.
angiomyolipoma (1 paper, 2021). A neoplasm with perivascular epithelioid cell differentiation often associated with tuberous sclerosis. "Expression and activity of vitamin A associated metabolic enzymes and RARβ were assessed in human kidney angiomyolipoma derived cell lines, primary lymphangioleiomyomatosis (LAM) tissue derived LAM cell lines." (PMID 34178631, 2021). "As patients with LAM disease are treated with rapamycin, and rapamycin is known to downregulate RARβ, RARβ protein expression levels were quantified in patient derived angiomyolipoma and LAM lung cell lines after 10 nM rapamycin treatment in the presence or absence of 2 μM RA." (PMID 34178631, 2021). "In the present study, we confirmed that downregulation of RARβ is not just a feature of TSC-deficient cell lines (angiomyolipoma, LAM primary cell lines) but it is characteristically present in primary LAM lung tissue sections." (PMID 34178631, 2021).
cervical adenocarcinoma (1 paper, 2025). An adenocarcinoma arising from the cervical epithelium. "Thirteen genes were found to be differentially expressed in cervical adenocarcinoma samples using microarray databases and literature reports, but only the MACC1, HOXC8, BCL2, and RARβ genes were the most representative of the expressed genes." (PMID 40361484, 2025). "We hypothesize that, even with the small number of samples used (randomized selection), there is strong evidence that the selected genes, HOXC6, HOXC8, RARβ, BCL2, and E6/E7, can be used as a pan early cervical adenocarcinoma test." (PMID 40361484, 2025). "In conclusion, this exploratory pilot study, through its robust and holistic analysis, provides evidence that MACC1, HOXC8, RARβ, BCL2, and E6/E7 could be promising molecular markers for the detection of cervical adenocarcinomas." (PMID 40361484, 2025).
cholesteatoma (1 paper, 2023). A pathologic process characterized by the proliferation of keratinizing squamous epithelium resulting in the accumulation of keratin and cells in the middle ear and/or mastoid.
chordoma (1 paper, 2013). Chordomas are rare malignant tumors arising from embryonic remnants of the notochord in axial skeleton. "By comparing methylation patterns of blood from healthy individuals and chordoma patients we found 20 significantly differentially methylated genes; 15 hypermethylated in chordoma (for example RASSF1, KL, RARB, HIC1, and FMR1) and 5 hypomethylated (HSD17B4, BAZIA, STAT1, NEUROGL, and JUP)." (PMID 23533570, 2013).
colon adenocarcinoma (1 paper, 2024). "Fen can be considered a suitable drug in colon adenocarcinoma since this disease is characterized by the downregulation of the retinoic acid receptor, and Fen has been proved to increase RARβ expression in a wide range of cancer cells, including colon adenocarcinoma." (PMID 39598544, 2024).
congenital diaphragmatic hernia (1 paper, 2022). A posterolateral defect of the diaphragm that allows passage of abdominal viscera into the thorax, leading to respiratory insufficiency and persistent pulmonary hypertension with high mortality. "RARB variants had been previously reported in association with autosomal recessive or autosomal dominant micro/anophthalmia, congenital diaphragmatic hernia, and varied additional clinical features that included spasticity and dystonia." (PMID 35937981, 2022).
endometrial atypical hyperplasia (1 paper, 2025). "Immunohistochemical analysis demonstrated that RARβ expression was significantly increased in uterine tissues from patients with progestin-insensitive EC or endometrial atypical hyperplasia." (PMID 40371351, 2025).
Esotropia (1 paper, 2024). A form of strabismus with one or both eyes turned inward ('crossed') to a relatively severe degree, usually defined as 10 diopters or more. "In comparison with BBJ (180K), RARB (retinoic acid receptor-β) was detected as a candidate at a significant level of p < 5 × 10−8 in the combined group of esotropia, exotropia, and idiopathic superior oblique muscle palsy." (PMID 39000095, 2024). "In a GWAS with BBJ (180K), RARB in chromosome 3 and HLA-F in chromosome 6 were suggested as candidates in the combined three-entities group with esotropia, exotropia, and idiopathic superior oblique muscle palsy." (PMID 39000095, 2024). "In comparison with the control cohort, BBJ (180K), RARB (retinoic acid receptor-β) was detected as a candidate at a significant level of p < 5 × 10−8 in the combined group of esotropia, exotropia, and idiopathic superior oblique muscle palsy." (PMID 39000095, 2024).
Ewing sarcoma (1 paper, 2024). A small round cell tumor that lacks morphologic, immunohistochemical, and electron microscopic evidence of neuroectodermal differentiation. "Expression of EZH2 and the RAR genes was either similar or lower in SS compared to other STS, except for RARβ, which showed higher levels in SS compared to Ewing sarcoma." (PMID 39550391, 2024).
heart failure (1 paper, 2022). Inability of the heart to pump blood at an adequate rate to meet tissue metabolic requirements. "Furthermore, selective ligand-mediated activation of RARB2 improved cardiac function in a heart failure model, supporting the notion that RARB could also contribute to ATRA-mediated cardioprotection during ACT." (PMID 36331922, 2022).
Hyperglycemia (1 paper, 2022). An increased concentration of glucose in the blood. "Possible explanations for this finding are a change in mRNA expression of the tested genes due to long-term hyperglycemia status or epigenetic regulations that control RARβ gene expression." (PMID 36101450, 2022).
hyperlipidemia (1 paper, 2026). "Surprisingly, podocyte-specific Rarβ deletion also increased key mRNAs and proteins involved in fatty acid uptake and lipid biosynthesis in the liver, promoting steatohepatitis and systemic hyperlipidemia." (PMID 41364431, 2026).
inflammatory bowel disease (1 paper, 2025). A spectrum of small and large bowel inflammatory diseases of unknown etiology. "Two disease-related pathways — inflammatory bowel disease (cfa05321; GATA3, TLR4) and cancer pathways (cfa05222; COL4A1, E2F3, RARB) — were also enriched." (PMID 40764990, 2025).
liver cancer (1 paper, 2017). An epithelial or non-epithelial malignant neoplasm that arises from the liver. "For examples, the dynamic expression of RARB, RARG similar with RARA can control the development and proliferation of liver cancer and HOXB8 from HOX family can play a prominent role as a brain tissue biomarker." (PMID 29033978, 2017).
meningioma (1 paper, 2015). A generally slow growing tumor attached to the dura mater. "In summary, this study provided evidence that p14ARF, RASSF1A, p15INK4B (CDKN2B), RUNX3, GATA6, p16INK4A (CDKN2A), NDRG2 and to lesser extent ATM and RARβ promoter methylation are associated with the development of meningiomas." (PMID 25648363, 2015). "The aim of this study was to evaluate the methylation status of 12 cancer-related genes, namely ERCC1, hMLH1, ATM, CDKN2B (p15INK4B), p14ARF, CDKN2A (p16INK4A), RASSF1A, RUNX3, GATA6, NDRG2, PTEN, and RARβ, in 44 meningioma samples of WHO grade I and II." (PMID 25648363, 2015).
mesothelioma (1 paper, 2025). A usually malignant and aggressive neoplasm of the mesothelium which is often associated with exposure to asbestos. "A meta‐analysis has further revealed that the APC gene is significantly hypomethylated in mesothelioma, while CDH1, ESR1, miR‐34b/c, PGR, RARβ, SFRP1, and WIF1 are significantly hypermethylated." (PMID 40904706, 2025).
myeloid leukemia (1 paper, 2012). A clonal proliferation of myeloid cells and their precursors in the bone marrow, peripheral blood, and spleen. "The RA-target gene RARβ plays a crucial role in mediating the growth-inhibitory and tumor suppressive effects of retinoids in various cancer cells, and RARβ is silenced in many tumors and myeloid leukemias including APL." (PMID 22685453, 2012).
nephrotic syndrome (1 paper, 2026). A collection of symptoms that include severe edema, proteinuria, and hypoalbuminemia; it is indicative of renal dysfunction. "Differentially altered expression of transcripts of retinoic acid receptors α, β, γ (Rarα, β, γ), which mediate the actions of all-trans retinoic acid (RA), is observed in glomeruli of nephrotic syndrome (NS) patients vs normal individuals, with Rarβ reduced and both RARα and RARγ increased." (PMID 41364431, 2026).
neuroendocrine carcinoma (1 paper, 2026). A malignant neuroendocrine neoplasm composed of cells containing secretory granules that stain positive for NSE and chromogranin. "However, it remains to be confirmed if RARβ may hold novel functions in neuroendocrine cancers, including NEPC." (PMID 40948103, 2026).
neuropathy (1 paper, 2022). A disorder affecting the nervous system that manifests with pain, tingling, numbness, and/or muscle weakness. "ATRA was found to suppress chemotherapy-induced neuropathy by increasing NGF and retinoic-acid-receptor beta (RAR-β) expression." (PMID 35565690, 2022).
Paget disease (1 paper, 2017). A malignant neoplasm composed of large cells with large nuclei, prominent nucleoli, and abundant pale cytoplasm (Paget cells). "RARβ hypermethylation was also associated with a higher percentage of Paget’s disease (31% vs 8%, p = 0.04)." (PMID 28893223, 2017).
Parkinson disease (1 paper, 2025). A progressive degenerative disorder of the central nervous system characterized by loss of dopamine producing neurons in the substantia nigra and the presence of Lewy bodies in the substantia nigra and locus coeruleus. "Many of the identified RARβ target genes associated with these pathways have been implicated in various neurodegenerative diseases, such as Alzheimer’s and Parkinson’s diseases." (PMID 40332055, 2025).
rectal tumours (1 paper, 2017). "Since T3 tumours represent the bulk of our CRC cohort, along with the fact that RARB methylation is lost through the progression of rectal tumours, our results could indicate that RARB hypomethylation is a biomarker for late stage CRC." (PMID 28700744, 2017).
seminoma (1 paper, 2022). A radiosensitive malignant germ cell tumor found in the testis (especially undescended), and extragonadal sites (anterior mediastinum and pineal gland). "Promoter hypermethylation of the RASSF1A and HIC1 genes was observed in resistant non-seminomas, while sensitive non-seminomas showed hypermethylation of MGMT and RARB." (PMID 35625709, 2022).
urinary bladder tumors (1 paper, 2008). "RARB has also presented high methylation frequencies in urinary bladder tumors (varying from 15% to 93%)." (PMID 18702824, 2008). "We observed hypermethylated CDH1, SFN, and RARB genes in the normal-adjacent tissue of urinary bladder tumor." (PMID 18702824, 2008).
viral infection (1 paper, 2024). "The expression of RA-regulated genes, such as RARA, RARB, CRABP1, HOXB1, and STRA6, were all downregulated after HSV-1 infection, thus further demonstrating that RA synthesis was inhibited by viral infection." (PMID 38989466, 2024).
tumor (165 papers, 2002 to 2026). "Research has indicated that RARβ is commonly repressed or silenced in multiple cancer types, and its loss has been linked with resistance to therapy and tumor progression." (PMID 37446908, 2023). "RARβ is a well-documented tumor suppressor, and loss of RARβ expression or silencing of its regulatory regions by epigenetic mechanisms is found in many types of cancers, including PDAC." (PMID 37198667, 2023). "Hypermethylation and the downregulation of RARB has been found in high-grade cancers and linked to tumor progression." (PMID 35611845, 2022). "In this paper, we confirmed that DLEU2 induces promoter methylation and loss of expression of the tumor inhibitor RARB and enhanced viability and mobility of CRC cells through the activation of the MAPK pathway." (PMID 35611845, 2022). "Previously we have reported that loss of RARα and RARβ expression in tumor tissue from advanced NSCLC patients was associated with a worse prognosis." (PMID 33324556, 2020). "Multivariate analyses further revealed that low RARβ expression (p = 0.001), distant metastasis (p = 0.001), tissue differentiation (p = 0.006), and tumor stage (p = 0.002) were associated with overall survival in CRC patients." (PMID 30944670, 2019). "RARB is an important tumor suppressor and loss of expression is associated with uncontrolled tumor growth and evasion of apoptosis in several tissues." (PMID 29851970, 2018). "RARβ regulates essential pathways associated with the tumor-suppressive effects of retinoids in various cells." (PMID 27011326, 2016). "In contrast to the protective effects of RARβ, studies have linked increased expression of RARα with formation of tumors of the breast and cervix, potentially by way of an estrogen-mediated pathway." (PMID 26462767, 2015). "Tumours with either LVI or distant metastasis were associated with lower methylation values of RARB." (PMID 25052224, 2014). "RARβ gene is a typical anti-tumor gene encoding retinoic acid receptor beta, a member of the thyroid-steroid hormone receptor subfamily of nuclear receptor superfamily." (PMID 24796328, 2014). "RARβ gene is a typical tumor suppressor gene encoding retinoic acid receptor beta, a member of the thyroid-steroid hormone receptor subfamily, which belongs to nuclear receptor superfamily." (PMID 24796328, 2014). "RARβ appears to have the dominant tumor suppressor role, whereas loss of RARβ expression is associated with tumor progression." (PMID 24379011, 2013). "Retinoids, e.g. 9cRA and atRA, and RARβ have long been associated with tumor suppressive properties such as reduced cell proliferation, inflammation, and solid tumor formation, as well as enhanced apoptosis." (PMID 22693611, 2012). "As a tumour suppressor gene, loss of RARβ has been associated with cancer progression and hence has been shown to be a potential antineoplastic therapeutic target." (PMID 22134508, 2012). "Combination of HDAC inhibitors and retinoids is associated with restoration of RARβ in tumours with a partially methylated promoter and greater antitumour activity as compared with single agents." (PMID 22134508, 2012). "Interestingly, RARB gene showed the strongest association compared to other tumor suppressor genes (OR = 15.25; 95% CI: 6.06–40.0; P < 0.001)." (PMID 33718129, 2021). "RARβ regulates essential pathways associated with the tumour-suppressive effects of retinoids in various epithelial cells and it has been suggested that RARβ signalling may act as a potential tumour suppressor." (PMID 33069074, 2020). "Although RARβ also showed weak expression in tumor-adjacent tissues, high RARβ protein expression was associated with a higher overall survival rate, indicating that RARβ expression might play a critical role in tumorigenesis among CRC patients." (PMID 30944670, 2019).
tumor (continued). "In addition, Kaplan–Meier analysis indicated that increased RARβ expression in cytoplasm (p = 0.001) and early tumor TNM stage (p = 0.030) was associated with a more favorable outcome in patients with CRC." (PMID 30944670, 2019). "In the case of the RARβ variants, expression is similar in the tissue samples and cell lines, as the average levels of RARβ1 are significantly more abundant in TN (Basal) than in all the other tumor sub-types (Fig7A)." (PMID 25888236, 2015). "Interestingly, RARβ is the receptor that is associated with the anti-tumour effects of RA." (PMID 34178631, 2021). "Interestingly, tumor-associated GSK-3β was inversely correlated with RARβ expression." (PMID 31938062, 2020). "Retinoic acid also remodels the tumor microenvironment by modulating angiogenesis, fibroblast activation, and immune responses, although stromal RARβ signaling can paradoxically promote tumor progression." (PMID 41721000, 2026). "Epigenetic effects of genistein include demethylation of promoter regions of tumor suppressor genes such as retinoic acid receptor beta (RAR-β), and O6-methylguanine methyltransferase (MGMT)." (PMID 40649790, 2025). "RAR exists in three isoforms—RARα, RARβ, and RARγ—each with distinct tissue distributions and roles: RARα is expressed in various tissues, RARβ plays a key role in neurogenesis and tumor suppression, and RARγ is vital for skin and bone development." (PMID 40926269, 2025). "For example, the expression of RARβ was downregulated in lung tumor tissues, suggesting a potential tumor-suppressive role of RARβ." (PMID 39311119, 2024). "Further, the ECDF for DMCs related to the RARB genes for benign and tumour sample types illustrated that the DMCs have increased beta values in the tumour samples compared to the benign samples." (PMID 39661598, 2024). "Our results differ from that observed in carcinoma cell lines, where RARB has been identified as a tumor suppressor and induction of RARB expression, either through transfection or treatment with pharmacological agents promotes growth inhibition." (PMID 39450403, 2024). "The methylation levels of the DMCs in cluster 2 that belong to the RARB genes suggest the median beta value is higher in the tumour sample type than in the benign sample type for all patients." (PMID 39661598, 2024). "knockdown of UHRF1 decreased the recruitment of DNMT1 to the CPG islands, thereby decreasing the maintenace of DNA methylation and re-elevating the epigenetic-silenced tumor suppressor genes such as RARB, CDH1, and PSP94." (PMID 36593255, 2023). "One such study determined the expression of RARs in normal and malignant tissues from 76 patients with NSCLC and showed that tumor cells have overexpressed RXRα and RARα and reduced RXRβ, RARβ, and RARγ." (PMID 35631448, 2022). "In contrast to all these findings, a report demonstrated the higher RARβ expression in cancer tissues, with a localized and uneven distribution in normal-appearing surrounding bronchial epithelium and inconsistencies with tumor tissues." (PMID 35631448, 2022). "It is possible that RARα and RARβ also play roles in WYC‐209‐induced tumor cell apoptosis and elucidation of their specific roles will require additional experiments." (PMID 36031407, 2022). "RARβ is the most well-known of the three RARs for its role as a tumor suppressor in epithelial cells." (PMID 35631448, 2022). "RARB is a tumor inhibitor protein involved in cell proliferation and differentiation, cell cycle progression, and apoptosis." (PMID 35611845, 2022). "NR2F1 is a known tumor dormancy marker, and RARβ and TGF-β signaling have been reported to induce dormancy." (PMID 35740627, 2022). "The expression of RARβ and RXRβ has been reported to be downregulated in NSCLC enabling their ability to evade apoptosis and have been associated with tumour development and prognosis." (PMID 33550205, 2021).